RANGRF (RAN guanine nucleotide release factor)
Description:
May regulate the intracellular trafficking of RAN. Promotes guanine nucleotide release from RAN and inhibits binding of new GTP by preventing the binding of the RAN guanine nucleotide exchange factor RCC1. Regulates the levels of GTP-bound RAN in the nucleus, and thereby plays a role in the regulation of RAN-dependent mitotic spindle dynamics. Enhances the expression of SCN5A at the cell membrane in cardiomyocytes.
Synonyms: RanGNRF; MOG1; HSPC165; HSPC236
Tractability: Antibody: UniProt places it where antibodies can reach, with high confidence; its Gene Ontology location is reachable by antibodies, with medium confidence. PROTAC: ubiquitination databases record sites on it.
Gene: Protein-coding gene on chromosome 17 (8,288,631 to 8,290,092, forward strand). Ensembl gene ENSG00000108961.
Subcellular location: Nucleus; Cytoplasm, perinuclear region; Cytoplasm; Cell membrane
Subcellular location (Human Protein Atlas): Nucleoplasm; Cytosol
Pathways (Reactome):
Muscle contraction: Phase 0 - rapid depolarisation
Gene Ontology:
Molecular function: channel activator activity; protein binding; small GTPase binding; sodium channel regulator activity; transmembrane transporter binding; guanyl-nucleotide exchange factor activity
Biological process: endoplasmic reticulum to Golgi vesicle-mediated transport; mitotic spindle assembly; positive regulation of membrane depolarization during cardiac muscle cell action potential; positive regulation of protein localization to cell surface; positive regulation of protein localization to plasma membrane; regulation of bundle of His cell action potential; regulation of cardiac muscle cell action potential involved in regulation of contraction; regulation of membrane depolarization; regulation of membrane depolarization during cardiac muscle cell action potential; regulation of sodium ion transmembrane transport; heart contraction; regulation of heart rate
Cellular component: caveola; cytoplasm; cytosol; nucleoplasm; nucleus; plasma membrane; rough endoplasmic reticulum; intercalated disc; perinuclear region of cytoplasm
Genetic constraint (gnomAD): Loss-of-function variants: 17 observed, 23.03 expected, observed/expected ratio (o/e) 0.74, 90% interval 0.5 to 1.11. The upper end of that interval is the gene's LOEUF score, 1.11, which puts it in group 4 of 6, group 1 being the genes least tolerant of losing a copy. Missense variants: 225 observed, 252.53 expected, observed/expected ratio (o/e) 0.89, 90% interval 0.8 to 1. Synonymous variants: 97 observed, 102.22 expected, observed/expected ratio (o/e) 0.95, 90% interval 0.8 to 1.12.
Gene-disease validity (ClinGen):
ClinGen rates the evidence that RANGRF causes each of these diseases.
Brugada syndrome (autosomal dominant): Refuted. A genetically heterogeneous condition characterized by complete or incomplete right bundle branch block accompanied by ST elevation in leads V1-V3.
Homologues: Orthologues: chimpanzee RANGRF (99% identical), macaque RANGRF (97% identical), rabbit RANGRF (91% identical), mouse Rangrf (88% identical), pig RANGRF (88% identical), rat Rangrf (88% identical), guinea pig RANGRF (86% identical), dog RANGRF (85% identical), tropical clawed frog rangrf (49% identical), zebrafish rangrf (44% identical).
Diseases named in the same sentence as RANGRF in open-access papers:
RANGRF is named in the same sentence as 13 diseases in open-access papers, as found by Europe PMC text mining. Sharing a sentence is not in itself a finding about the gene and the disease. The quoted sentences say what the papers report.
Brugada syndrome (7 papers, 2013 to 2025). "Finally, the RANGRF gene, previously linked to Brugada syndrome, represents a novel finding in this context." (PMID 39886381, 2025). "In Brugada syndrome, AAV9-mediated overexpression of MOG1 (Ran guanine nucleotide release factor), a critical modulator of Nav1.5 trafficking, was employed in a knock-in mouse model harboring the SCN5AG1746R mutation." (PMID 40843724, 2025).
cardiac arrhythmia (1 paper, 2021). Any disturbances of the normal rhythmic beating of the heart or MYOCARDIAL CONTRACTION. "MiR-3144 acts on tumor suppression in high-risk human papilloma virus infection and was recently identified as the regulatory miRNA for RANGRF in human cardiac myocytes, for which, the involvement in cardiac arrhythmia was described." (PMID 34827715, 2021).
RANGRF also shares sentences with these, for which no sentence is quoted: atrial fibrillation (2 papers); autoimmune encephalitis (1); Autoimmunity (1); Heart block (1); human papilloma virus infection (1); relapsing (1); sudden cardiac death (1); sudden infant death syndrome (1); tetanus (1); tumor (1); Ventricular arrhythmia (1).